PKP2 (plakophilin 2)
Diseases named in the same sentence as PKP2 in open-access papers (continued):
Sharing a sentence is not in itself a finding about the gene and the disease.
tumor (13 papers, 2010 to 2026). "Meanwhile, when compared with normal group, the HSPA6, NOTCH3 and PKP2 expression were significantly increased in LUAD tumor group, but GPD1L and SMAD9 expression were dramatically decreased in control group (all P < 0.001)." (PMID 40796704, 2025). "This downregulation of PKP2 disrupts intercellular connections and promotes tumor cell invasion and metastasis, consistent with previous studies identifying PKP2 as a tumor suppressor." (PMID 40046740, 2025). "Amongst the differentially expressed EMT genes from that study, we find overlap with PTPRK-regulated genes including TGFB1, COL6A1, GPX3 and KLK10, as well as genes encoding LSR and PKP2, both of which are hyperphosphorylated in PTPRK KO tumours." (PMID 38904097, 2024). "The relationships between the expression of PKP2/3 and tumor-infiltrating lymphocytes (TILs) and immunomodulators were analyzed by Spearman correlation using TISIDB database." (PMID 33088217, 2020). "In addition, the expression of serum HSPA6, NOTCH3 and PKP2 were significantly up-regulated in the LUAD tumor group, while GPD1L and SMAD9 showed a significant down-regulation trend when compared to the control group." (PMID 40796704, 2025). "PKP2 accelerates tumor progression by promoting EGFR phosphorylation and activation." (PMID 40433361, 2025). "The results showed that, compared to normal samples, HSPA6 and NOTCH3 were dramatically increased, while GPD1L, PKP2, and SMAD9 were dramatically decreased in tumor samples in both the CRC training dataset and the CRC validation dataset (all P < 0.05)." (PMID 40796704, 2025). "In the CRC tumor group, the expression levels of HSPA6 and NOTCH3 protein were dramatically up-regulated, while GPD1L, PKP2, and SMAD9 protein were dramatically down-regulated (all P < 0.05)." (PMID 40796704, 2025). "Compared to the control group, serum levels of HSPA6 and NOTCH3 were significantly elevated in the CRC tumor group, whereas GPD1L, PKP2, and SMAD9 exhibited a marked decrease." (PMID 40796704, 2025). "The result demonstrated a significant increase in HSPA6 and NOTCH3 expression, but a significant decreased in GPD1L, PKP2 and SMAD9 in CRC tumor group when compared to those in normal group (all P < 0.001)." (PMID 40796704, 2025). "PKP2, TXN, and ZNF292 are also abnormally expressed in tumors and induce radioresistance of tumor cells." (PMID 37101691, 2023). "Subsequently, we applied RT-PCR to detect the expression level of GAPDH, GNPNAT1, HTATIP2, MFI2, PKP2, RGS20, and CHRDL1 in these 10 tumor tissues." (PMID 35186082, 2022). "Similarly, in the LUAD tumor group, HSPA6, NOTCH3, and PKP2 protein expression were dramatically stimulated, whereas GPD1L and SMAD9 protein expression were dramatically suppressed (all P < 0.05)." (PMID 40796704, 2025). "Moreover, compared to normal samples, HSPA6, NOTCH3, and PKP2 were dramatically overexpressed, while GPD1L and SMAD9 were dramatically de-expressed in tumor samples in both the LUAD training dataset and the LUAD validation dataset (all P < 0.05)." (PMID 40796704, 2025). "On the other hand, overexpressed genes like PKP2 and CDKN3 may promote tumor progression by affecting calcium-dependent cell-cell adhesion and cell cycle regulation, respectively." (PMID 40433361, 2025). "Similarly, PKP2 and GPD1L retained significance in LUAD, supporting their utility as biomarkers even when accounting for tumor progression." (PMID 40796704, 2025). "In addition, ERO1A, PKP2, and MERTK have been proved to promote the progress and drug resistance of NSCLC by enhancing the activation of tumor and PI3K, EGFR, and other signal pathways." (PMID 37101691, 2023). "The results suggested that the level of PKP2 mRNA was associated with the tumor stages (P < 0.05), while the levels of PKP1 and PKP3 mRNA were not significantly different among the tumor stages (P > 0.05)." (PMID 33088217, 2020).
tumor (continued). "There was no observable clinical association with PKP1 or PKP2 expression; however, low PKP3 level and poor prognosis appeared to correlate with regards to node number and tumor stage." (PMID 21194493, 2011). "We identified several components of desmosomes – Dsp, Dsg2, desmocollin 2 (Dsc2; MGI: 103221), and plakophilin 2 (Pkp2; MGI: 1914701) – whose expression was significantly downregulated in the highly invasive tumor lesions that develop in the RT2 mouse model of PNET." (PMID 20862307, 2010). "Finally, while the five biomarker proteins (HSPA6, NOTCH3, PKP2, SMAD9, and GPD1L) are primarily intracellular, their presence in serum could potentially be attributed to tumor derived extracellular vesicles or cell lysis during tumor progression." (PMID 40796704, 2025). "Decreased PKP2 and PKP3 expression may be an early step in tumor transformation." (PMID 21194493, 2011).
infection (6 papers, 2017 to 2025). The state of being infected such as from the introduction of a foreign agent such as serum, vaccine, antigenic substance or organism. "Conversely, interactome analysis also allows discovering host proteins that protect against infection such as Plakophilin 2 (PKP2), a natural inhibitor of IAV polymerase complex." (PMID 35531299, 2022). "Overexpressed PKP2 decreased infection (by 3- to 4-fold) and siRNA experiments increased infection levels (by 2- to 3-fold)." (PMID 33810083, 2021). "First, three FLAG-tagged armadillo repeat-containing proteins, PKP2, PKP4 (a.k.a. p0071) and β-catenin (also known as CTNNB1) were transfected into HEK293 cells, followed by infection with the PR8-Gluc." (PMID 28169297, 2017). "Following infection, PB1 was expressed and co-localized with PKP2 in the nucleus." (PMID 28169297, 2017). "To assess the effect of PKP2 restoration on desmosomal integrity, we next transduced the PKP2 mutant iPS-cell-derived CMs with either AAV6–PKP2 or an empty AAV6 vector (AAV6-ctr) and performed mRNA and protein analysis at 4 days and 7 days post-infection, respectively." (PMID 38665939, 2023).
adenocarcinoma (2 papers, 2011 to 2022). A common cancer characterized by the presence of malignant glandular cells. "PKP2 has been reported to be overexpressed in all adenocarcinomas." (PMID 34949159, 2022). "One study reported PKP2 as expressed in all adenocarcinomas." (PMID 21194493, 2011).
cardiovascular disorder (1 paper, 2021). A disease involving the cardiovascular system.
gastrointestinal disorders (1 paper, 2022). "In addition, four genes PDE4D, PKP2, NLGN1 and ALDH1B1 may be candidate genes for congenital heart defects or gastrointestinal disorders in OSH." (PMID 36302822, 2022).
PKP2 also shares sentences with these, for which no sentence is quoted: hypertrophic cardiomyopathy (5 papers); cardiac arrhythmias (4); catecholaminergic polymorphic ventricular tachycardia (4); ventricular fibrillation (3); acute myocarditis (2); Cardio-cutaneous syndromes (2); familial hypercholesterolemia (2); Naxos disease (2); acute pneumonia (1); bacterial infection (1); cardiac arrest (1); Carvajal syndrome (1); clear cell carcinoma (1); congenital heart disease (1); coronary heart disease (1); Duchenne muscular dystrophy (1); endometrioid carcinoma (1); familial thoracic aortic aneurysms and dissections (1); fibrosis (1); fracture (1); genetic disease (1); influenza (1); long QT syndrome 3 (1); lymph node metastasis (1); Marfan syndrome (1); melanoma (1); meningioma (1); mucinous carcinoma (1); ovarian serous cystadenocarcinoma (1); polymorphic ventricular tachycardia (1).
A further 6 diseases each share a sentence with PKP2 in 1 paper.